HIF1A (hypoxia inducible factor 1 subunit alpha)
Diseases named in the same sentence as HIF1A in open-access papers (continued):
Sharing a sentence is not in itself a finding about the gene and the disease.
liver cancer (continued). "In this study, we employed a combination of in silico molecular docking and in vitro cell validation experiments to identify three ferroptosis suppressor genes, AR, HIF1A, and CA9, as promising components of a survival prognosis model during the metformin‐induced ferroptosis process in liver cancer." (PMID 40583627, 2025). "Administration of HIF-1α inhibitors can block the upregulation of MMP2 and delay the progression of liver cancer, providing further verification of the conclusion that the HIF-1α/MMP2 or HIF-1α/MMP9 signaling pathways are involved in the occurrence and development of liver cancer." (PMID 40563539, 2025). "More importantly, we employed the chemical induction method using CoCl2 as it stabilizes explicitly the expression of the HIF-1A subunit without activating HIF-2A in liver cancer cell lines." (PMID 39567394, 2024). "Notably, SFN exerts anti-angiogenic effects by inhibiting hypoxia-induced HIF-1α and VEGF expression in several cancers, including prostate, colon, and liver cancers." (PMID 36899823, 2023). "Previous studies have shown that in liver cancer cells, SSD may inhibit the expression of COX-2 through the P-STAT3/HIF-1α pathway and reduce the expressions of P-STAT3 and HIF-1α, which inhibits the proliferation of HCC SMMC-7721 cells." (PMID 37489008, 2023). "In addition, CCL5 and HIF1α were positively correlated in clinical HCC samples, and high HIF1α expression was closely connection with poor prognosis in liver cancer patients." (PMID 35589690, 2022). "Moreover, under hypoxia, phosphorylated STAT3 enhances HIF1α stability to increase HIF1α-mediated VEGF secretion, promoting angiogenesis in renal carcinoma and liver cancer." (PMID 35123491, 2022). "In the hypoxic environment of liver cancer, USP14 can enhance the transcriptional activity of HIF-1α and the stability of HIF-1α through deubiquitination, which in turn promotes the migration and invasion of HCC cells in a HIF-1α-dependent manner." (PMID 35875077, 2022). "HIF1A siRNA was transfected into HepG2 cells under hypoxic conditions, downregulating HIF1A and its target gene VEGF at the mRNA and protein levels, with an antiangiogenic effect on liver cancer." (PMID 35659268, 2022). "Hif1-α and VEGF are over-expressed in many tumors including liver cancer." (PMID 34113483, 2021). "In liver cancer cells, sorafenib down-regulates the expression of HIF-1α, but up-regulates the expression of HIF-2α, with a final effect of changing the hypoxic response from the HIF-1α-dependent to the HIF-2α-dependent pathway." (PMID 35096574, 2021). "HIF1α/HSP90α and RIPK1 were almost highly expressed in liver cancer tissues." (PMID 33440739, 2021). "Correspondingly, we found that overexpression of PTEN or Myr-Akt1 exhibited no influence on HIF-1α level in liver cancer cells." (PMID 34897283, 2021). "Our study provides evidence that under hypoxic conditions CK inhibited the expression of Bclaf1 in Bel-7404 and Huh7 cells, promoted the degradation of HIF-1α ubiquitination, and inhibited the HIF-1α-mediated cellular glycolysis pathway to inhibit the proliferation of liver cancer cells in vitro." (PMID 33363466, 2020). "Furthermore, we detected HIF-1α and HMGB1 protein levels in SMMC-7721 and Huh7 human liver cancer cells after TNF-α (10ng/mL) treatment." (PMID 32328193, 2020). "In addition, the effect of melittin on CoCl2-induced EMT and migration of liver cancer cells was reversed, at least partly, by the activator of Akt, suggesting that melittin inhibits hypoxia-induced EMT and VM formation through HIF-1α/Akt pathway." (PMID 31057657, 2019). "Moreover, HIF-1α has been shown to upregulate A2B and P2Y2 expression in liver cancer." (PMID 36942939, 2023).
liver cancer (continued). "Furthermore, OTUD6B is identified as a direct target of HIF‐1α and the negative feedback loop between OTUD6B and HIF‐1α regulates liver cancer metastasis under hypoxia." (PMID 32328410, 2020). "However, a study using AMPKα siRNA on HEP2G and Huh7 liver cancer cell lines showed that AMPK activation did not affect HIF-1α." (PMID 32806648, 2020). "SB3 acts by (i) up-regulating HIF-1α transcription, facilitating cell survival in a harsh microenvironment and promoting angiogenesis, (ii) increasing HIF-2α stabilization via direct/selective NEDDylation, promoting proliferation of liver cancer cells, and favoring HCC progression." (PMID 31817100, 2019). "However, many treatment methods for liver cancer usually induce a hypoxia microenvironment, including TACE and radiofrequency ablation, and thereafter promote tumor angiogenesis and metastasis, in part related to the accumulation of HIF-1α." (PMID 31057657, 2019). "With regards to expression at a molecular level, studies have demonstrated that liver cancer is regulated more by HIF-1α; however, in vascular endothelial cells, such as human umbilical vein endothelial cells (HUVEC), the level of IL-8 regulation is similar to that of HIF-1α." (PMID 28053598, 2017).
renal carcinoma (149 papers, 2004 to 2025). A carcinoma arising from the epithelium of the renal parenchyma or the renal pelvis. "Under normoxic conditions, constitutively high protein levels of HIF-1α in the pVHL-deficient renal carcinoma cell line RCC-4 were unaffected by depletion of USP25." (PMID 35440539, 2022). "HIF-1α is reported to suppress apoptosis and to promote tumorous progression in renal cancer cells; especially associated with metastatic tumors of ccRCC." (PMID 34926261, 2021). "Our study for the first time highlighted the critical role of SNHG12-miR-199a-5p-HIF1α axis underlying the malignant features of renal carcinoma." (PMID 31114448, 2019). "We found that renal carcinoma cells RCC4 line which carries pVHL loss-of-function mutation was insensitive to ADI-induced HIF-1α turnover." (PMID 28883660, 2017). "The distinct contributions of HIF-1α versus HIF-2α toward apoptosis were then investigated using VHL-deficient renal carcinoma cell lines and manipulation of HIF-1α and HIF-2α expression." (PMID 25729330, 2015). "O2-independent mechanisms can also stabilize HIF1α, i.e. mutations in the Von Hippel-Lindau (pVHL) tumor suppressor gene in renal carcinoma." (PMID 25605240, 2015). "Recently, the naphthalene derivative CL67 has been reported to selectively interact with the HIF1A G4 and to cause down-regulation of HIF1A expression levels in renal cancer and osteosarcoma cells." (PMID 24108400, 2013). "HIF-1α is essential for tumorigenesis in VHL-deficient renal carcinoma cells." (PMID 40011447, 2025). "Moreover, macrophage HIF-1α has been identified as an independent prognostic indicator for renal cancer, being associated with highly invasive or deteriorating renal tumors." (PMID 38292868, 2024). "To test this hypothesis, we investigated whether VBP1 regulated HIF-1α in the pVHL-deficient RCC4 renal carcinoma cells, which demonstrate high endogenous levels of HIF-1α and HIF-2α proteins." (PMID 37201586, 2023). "High levels of HIF-1α protein increase the susceptibility to ferroptosis in renal carcinoma cells." (PMID 35205167, 2022). "Cancer genome analyses have not yet defined clusters of mutations typical of oncogenic activation in genes encoding any HIF subunit; to date the clearest evidence for mutational selection on HIF in cancer is an excess of inactivating mutations in HIF-1α in the context of pVHL-defective renal cancer." (PMID 24491179, 2014). "Considering that Per2 is reported to have tumor-suppressor properties, it is possible that HIF1α increases Per2 transcriptional activity thereby inhibits tumor proliferation in contrast to the previous finding that HIF-mediated gene pathway is the main risk-factor of tumor growth in renal cancer." (PMID 25333958, 2014). "The results showed that L-2-HG increased the lactylation modification of HIF1A and enhanced the resistance of renal cancer cells to ferroptosis, thereby increasing cell proliferation, migration, and invasion." (PMID 41198650, 2025). "Similar effects were observed upon TQ treatment in renal cancer cells, where TQ reduced HIF-1α protein levels, and this reduction effect was mediated via the ubiquitination-proteasome-dependent pathway." (PMID 41303508, 2025). "Under hypoxic conditions, TQ reduces HIF-1α protein levels and transcriptional activity by promoting its ubiquitin-proteasome-mediated degradation, disrupting hypoxia adaptation in renal cancer cells." (PMID 41303508, 2025). "We first confirmed that DMF can upregulate PD-L1 expression in RAG cells, a mouse renal cancer cell line, through the HIF-1α/p300/PKM2 transcriptional complex." (PMID 40461489, 2025). "RENCA and RAG renal carcinoma cells were treated with L-2-HG to investigate its impact on histone lactylation modification and HIF1A expression." (PMID 41198650, 2025). "Hypoxia-inducible factors (HIF-1α and HIF-2α) are upregulated under intermittent hypoxic conditions and have been implicated in the progression of bladder, prostate, and renal cancers." (PMID 41439855, 2025).
renal carcinoma (continued). "Additional investigation uncovered that TRIM21 hindered cell proliferation and metastasis by facilitating the breakdown of HIF-1α, hence suppressing cell glycolysis in renal cancer cells." (PMID 38773612, 2024). "It has also been confirmed that the expression of HIF-1α is elevated in renal cancer tissues and is involved in renal carcinogenesis and various biological processes." (PMID 39068456, 2024). "Recent work indicated that hypoxia promotes Lgals3 activity depending on HIF-1α in renal carcinoma cells." (PMID 39595213, 2024). "Similarly, the downregulation of Hif1a, a master regulator of the hypoxic response, suggests that our eKET diet may disrupt the adaptive mechanisms that allow tumors to thrive in low-oxygen environments, a hallmark of aggressive renal cancers." (PMID 39410010, 2024). "Previous research has demonstrated that TRIM21 can facilitate HIF‐1α ubiquitination, leading to attenuation of renal cancer progression." (PMID 39556022, 2024). "In our study, we observed a significant positive correlation between PLOD2 and HIF1A in renal cancer tissues, with HIF1A promoting the expression of PLOD2." (PMID 38008826, 2023). "Quinones: In renal cancer cells, thymoquinone (TQ) reduced protein level of HIF-1α through a ubiquitination-proteasome-dependent pathway and inhibited the transcriptional activity of HIF-1α." (PMID 36339566, 2022). "It is possible that HIF-1α mediates B7-H4 induced expression in renal cancer cell lines upon treatment with targeted therapies." (PMID 35563753, 2022). "Mutational inactivation of VHL is the earliest genetic event in renal cancer, leading to the accumulation of HIF-1α and HIF-2α transcription factors." (PMID 36364144, 2022). "For example, mutations that result in inability of pVHL to bind to HIF-1α will result in HIF-1 activation in the presence of oxygen, as was shown for pVHL mutations in renal carcinoma and hemangioblastoma." (PMID 35372069, 2022). "Array gene expression analysis of the VEGF pathway of HUVECs treated with renal cancer exosomes revealed that the change of HIF1α was significant." (PMID 34179017, 2021). "To this end, we detected the expression and localization of HIF-1α protein in renal normal/ccRCC tissues and renal cancer cells." (PMID 34926261, 2021). "MITFE318K germline hotspot mutation was shown to impair MITF SUMOylation, to increase the affinity for the hypoxia-induced HIF1A promoter, and to enhance migration, invasion, and clonogenicity of melanoma and renal cancer cells." (PMID 34067022, 2021). "Overexpression of NDRG2 upregulated the expression of pVHL along with downregulation of HIF-1α and attenuated proliferation and invasion in renal cancer cells." (PMID 34013046, 2021). "TKI-resistant renal cancer had a weaker inhibitory effect on HIF1α due to its low expression level of miR-549a, resulting in greater vascular permeability and angiogenesis of endothelial cells." (PMID 34179017, 2021). "HIF-1α has been found to be overexpressed in a variety of human cancers, such as colon, breast, gastric, lung, skin, ovarian, pancreatic, prostate, and renal carcinomas." (PMID 32375802, 2020). "We noted that HIF-1α, which is highly expressed in VHL-mutated renal cancer cells, acts as a downstream effector of QKI." (PMID 32047543, 2020). "The HIF-1α protein is overexpressed in various common solid malignant tumors, including breast, colon, gastric, lung, skin, ovarian, pancreatic, prostate, and renal carcinomas compared with their respective normal tissues." (PMID 31711497, 2019). "The elevated HIF-1α expression has been reported in many cancers including breast, liver, colon, ovarian, brain, prostate, bladder, lung and renal cancer." (PMID 30746305, 2019). "Overall, our finding suggested that TQ, as an HIF-1α inhibitor, is a potential natural compound involved in clearance of hypoxic renal cancer cells." (PMID 30832444, 2019).
renal carcinoma (continued). "We characterize aberrant over-expression of SNHG12 in renal carcinoma, which competed with miR-199a-5p to positively regulate HIF1α." (PMID 31114448, 2019). "Overproduction of HIF-1α in VHL-defective renal carcinoma cells suppresses tumor formation, while overproduction of HIF-2α promotes tumor growth." (PMID 29560117, 2018). "In renal cancers, HIF1α and −2α seem to play an opposing role, with HIF1α acting as a tumor suppressor and HIF2α behaving as an oncogene." (PMID 29535842, 2018). "More recently, we have shown that Zn2+ induces expression of HIF1α in normal HK-2 renal tubular cells as well as in ACHN renal cancer cells." (PMID 29492208, 2018). "The only study using renal cancer cells (RCC4) demonstrated that Zn2+ down-regulates expression of HIF1α and its downstream target VEGF in vivo and in vitro." (PMID 28686686, 2017). "In particular, HIF-1α was first found to interact and co-localize with lysosome-associated membrane protein type 2A in HK2 human kidney and RCC4 renal cancer cells." (PMID 29230384, 2017). "Preliminary investigation revealed that ZnCl2 increases the expression of HIF1α in the immortalized human proximal tubular cell line HK-2 and in the renal cancer cell line ACHN in a dose dependent manner." (PMID 28686686, 2017). "Studies in renal carcinomas have demonstrated that BNIP3 expression correlates positively to HIF-1α activity, but negatively to HIF-2α suggesting distinct roles in apoptotic signaling as well." (PMID 29045486, 2017). "For instance, calcium-activated phosphatase calcineurin prevented RACK1 dimerization and subsequent HIF-1α degradation in Hek293 and renal carcinoma RCC4 cells." (PMID 29230384, 2017). "On a more positive note, the identification of HIF-2 allosteric inhibitors has validated this as a target in renal cancer, whilst HIF-1α/p300 helix mimetics have been shown to act in mouse tumour models." (PMID 28878873, 2017). "Here, we show that p62 knockdown reduces cell growth and the expression of glycolytic genes in a manner that depends on HIF1α activity in renal cancer cells." (PMID 26743088, 2016). "In the present study, we have explored a previously uncharacterized relationship between p62 and HIF1α, and demonstrated that p62 regulates energy metabolism and colony formation in soft agar by regulating HIF1α levels in renal cancer cells." (PMID 26743088, 2016). "HDAC4 interacts with hypoxia-inducible factor 1α (HIF-1a) and mediate angiogenesis in renal carcinoma cells." (PMID 25504437, 2015). "In renal carcinoma, loss of VHL can lead to sustained up-regulation of both HIF-1α and HIF-2α isoforms in some tumors or only HIF-2α in other tumors, but not solely HIF-1α." (PMID 25729330, 2015). "Our analyses of the metabolome expand on this prior knowledge and establish the ability of HIF1α to mediate altered tumor metabolism in an informative renal cancer model, the TRACK mouse." (PMID 25830305, 2015). "Rather, in pVHL-defective renal cancer, a small but significant excess of inactivating mutations has been observed in HIF-1α and reduction in HIF-1α gene dosage through deletion of a region of chromosome 14q is common." (PMID 24491179, 2014). "Considering the results that the Per2 circadian rhythm was shown only in Caki-2 cells, which contained BMAL1, CLOCK, and HIF1α protein, it is possible that HIF1α is related to the Per2 circadian rhythm in renal cancer cell lines." (PMID 25333958, 2014). "It is well established that hypoxia regulates glycolysis and mitochondrial respiration through up-regulation of PDK1 via HIF-1α in human breast and renal cancer cell lines." (PMID 23050013, 2012). "Previously it has been shown that HIF-1α has anti-proliferative effects in VHL defective renal cancer cells." (PMID 21386837, 2011). "HIF-1α downregulation induced by zinc was ineffective in human RCC4 VHL-null renal carcinoma cell line; likewise, the HIF-1αP402/P564A mutant was resistant to zinc treatment." (PMID 21179202, 2010).